IGKV3D-7 (immunoglobulin kappa variable 3D-7)
Description:
V region of the variable domain of immunoglobulin light chains that participates in the antigen recognition. Immunoglobulins, also known as antibodies, are membrane-bound or secreted glycoproteins produced by B lymphocytes. In the recognition phase of humoral immunity, the membrane-bound immunoglobulins serve as receptors which, upon binding of a specific antigen, trigger the clonal expansion and differentiation of B lymphocytes into immunoglobulins-secreting plasma cells. Secreted immunoglobulins mediate the effector phase of humoral immunity, which results in the elimination of bound antigens. The antigen binding site is formed by the variable domain of one heavy chain, together with that of its associated light chain. Thus, each immunoglobulin has two antigen binding sites with remarkable affinity for a particular antigen. The variable domains are assembled by a process called V-(D)-J rearrangement and can then be subjected to somatic hypermutations which, after exposure to antigen and selection, allow affinity maturation for a particular antigen.
Synonyms: IGKV3D7; L25
Gene: Immunoglobulin variable (V) gene on chromosome 2 (90,234,812 to 90,235,370, forward strand). Ensembl gene ENSG00000228325.
Subcellular location: Secreted; Cell membrane
Subcellular location (Human Protein Atlas): Cytosol; Plasma membrane; Predicted to be secreted
Gene Ontology:
Biological process: immune response
Cellular component: extracellular region; immunoglobulin complex; plasma membrane
Homologues: Orthologues: mouse Igkv18-36 (65% identical), rat Igkvl13 (62% identical). Paralogues in human: IGKV3OR2-268 (92% identical), IGKV3-7 (88% identical), IGKV3-11 (85% identical), IGKV3-15 (85% identical), IGKV3-20 (83% identical), IGKV3D-11 (83% identical), IGKV3D-15 (83% identical), IGKV3D-20 (82% identical), IGKV1-39 (66% identical), IGKV1D-39 (66% identical), IGKV1D-8 (66% identical), IGKV1-6 (65% identical), and 81 more.